ANGPTL4 (angiopoietin like 4)
Diseases named in the same sentence as ANGPTL4 in open-access papers (continued):
Sharing a sentence is not in itself a finding about the gene and the disease.
Obesity (104 papers, 2008 to 2026). Accumulation of substantial excess body fat. "For example, FABP4 upregulates ANGPTL4 in obesity-associated triple-negative breast cancer, promoting angiogenesis and chemoresistance." (PMID 40717587, 2025). "On the other hand, studies have also reported increased circulating levels of ANGPTL3, ANGPTL4 or ANGPTL8 in association with metabolic syndrome in cohorts with obesity, diabetes and/or dyslipidemia." (PMID 38879166, 2024). "Hepatocyte‐specific suppression of Angptl4 expression was recently shown to improve obesity‐associated diabetes and mitigate atherosclerosis in mice." (PMID 36967480, 2023). "ANGPTL4 deficiency by genetic knockdown or treatment with a neutralizing antibody led to a significant reduction in obesity‐induced angiogenesis and tumour growth." (PMID 35285130, 2022). "We also investigated how adipocyte-specific loss of ANGPTL4 affected body weight, glucose tolerance, and insulin resistance in the setting of either 3 or 6 months of high-fat diet feeding and obesity." (PMID 33846453, 2021). "The main novel finding of our study is the relationship observed between the circulating concentrations of ANGPTL4 and the obesity-associated endothelial dysfunction." (PMID 34440242, 2021). "ANGPTL4 serum levels are significantly higher in adults with abnormal glucose tolerance and are associated with central and total obesity and insulin resistance by the Homeostatic Model Assessment of Insulin Resistance (HOMA IR)." (PMID 32878157, 2020). "We also examined the associations between muscle ANGPTL4 and obesity, aerobic capacity, glucose tolerance and insulin sensitivity." (PMID 32878157, 2020). "ANGPTL4 expression in skeletal muscle is associated with serum ANGPTL4, glucose metabolism and obesity." (PMID 32878157, 2020). "Recent studies have shown that plasma levels of ANGPTL-4 is higher in individuals with obesity and type 2 diabetes, and it is positively associated with obesity-related parameters in adult populations." (PMID 31207920, 2019). "In the multiple linear regression analysis, the optimal model that best explained the ANGPTL-4 data included obesity diagnostic, FFA, LDL-cholesterol, vitamin-D and total cholesterol, with an adjusted R2 value of 0.30." (PMID 31207920, 2019). "Third, in subjects with obesity and BMI loss, the percent change of ANGPTL-4 was positively correlated with the percent change of FFA and negatively with the percent change of total cholesterol and HDL-cholesterol." (PMID 31207920, 2019). "Recent studies have highlighted the strong association between ANGPTL-4 levels and obesity in adults." (PMID 31207920, 2019). "Supporting the role of ANGPTL-4 in obesity, associations between ANGPTL-4 gene polymorphism and a high percentage of body fat, low levels of TG, or disrupted serum lipid concentrations have been reported." (PMID 31207920, 2019). "In the second cohort, which included only children with obesity (n = 20, age 5–18 years) followed up for two years after an intervention for weight loss, in which we performed a longitudinal study measuring ANGPTL-4 before and after BMI-loss." (PMID 31207920, 2019). "Overall, our findings suggest that loss of ANGPTL4 promotes (visceral) obesity yet, by raising insulin levels, reduces glucose intolerance, and that this effect is partly dependent on the gut bacteria." (PMID 29502266, 2018). "Unfortunately, the study of ANGPTL4 in diet-induced obesity and associated metabolic dysfunction is hampered by the massive acute phase response and the development of lethal chylous ascites in Angptl4−/− mice fed a high-fat diet." (PMID 29502266, 2018). "In conclusion, we show that loss of ANGPTL4 in mice with diet-induced obesity promotes visceral obesity while improving glucose tolerance." (PMID 29502266, 2018).
Obesity (continued). "The objective of this study was to investigate the association of ANGPTL4 variants (E40K and T266M) with triglyceride levels and with cardiovascular risk factors, such as metabolic syndrome (MetS) and obesity in type 2 diabetic Tunisian population." (PMID 27004807, 2016). "We therefore conclude that the effect of the ANGPTL4 E40K polymorphism is unlikely diminished to any substantial degree by the independent effects of obesity and T2D on triglyceride levels." (PMID 21714923, 2011). "Angptl4, a recently identified adipokine, exerts pleiotropic effects on glucose and lipid metabolism, improves insulin resistance, and is implicated in various risk factors for heart failure, including obesity, diabetes, and coronary heart disease." (PMID 40476003, 2025). "Elevated ANGPTL4 levels have been reported in the plasma of both HFpEF and HFrEF patients, suggesting that more phenotypically fine-grained plasma studies are needed to dissect the association of ANGPTL4 with the HF phenotypes and relevant comorbidities like obesity and atherosclerosis." (PMID 39311911, 2024). "Furthermore, ANGPTL4 expression levels are positively correlated with an increased risk of T2D and obesity-related diabetic phenotypes." (PMID 39176085, 2024). "As noted for WD-fed MR-Intact mice, WD also downregulated genes associated with extracellular matrix in SMC-MR-KO mice (Online Resources 26 and 27) and top upregulated genes also included those implicated in diabetes and obesity, such as Cd36, Txnip, Angptl4, Cyp1a1, and Fabp4." (PMID 36988733, 2023). "The effects of adipocyte-specific ANGPTL4-deficiency on triglyceride and glucose homeostasis were determined after 12 weeks of high-fat feeding, as well as after 6 months of high-fat feeding to model a chronic state of obesity." (PMID 33846453, 2021). "Taken together, these findings suggest that different mechanisms are involved in the dysregulation of ANGPTL3 and ANGPTL4 in patients with increased adiposity or, alternatively, that diverse metabolic abnormalities stem from the obesity-associated changes in circulating ANGPTL3 and ANGPTL4." (PMID 34440242, 2021). "provided evidence that the level of plasma ANGPTL4 was associated with obesity in humans." (PMID 33498410, 2021). "As changes in energy expenditure play a role in the pathogenesis of obesity, we asked if adipocyte-specific loss of ANGPTL4 would lead to changes in energy expenditure, oxygen consumption (VO2), carbon dioxide production (VCO2), or respiratory quotient (RQ; VCO2/VO2)." (PMID 33846453, 2021). "Also, ANGPTL4 was positively correlated with obesity-associated characteristics such as BMI, waist circumference, and fat mass, as well as with altered glucose tolerance-associated hallmarks (glycated haemoglobin (HbA1c), HOMA-IR, and fasting TRG)." (PMID 30944669, 2019). "The results of the present work suggest that ANGPTL-4 might be considered as a potential biomarker for the risk of obesity in children as well as alterations on lipid and glucose metabolism as obesity co-morbidities." (PMID 31207920, 2019). "In conclusion, in pregnant women with overweight and obesity, an increase in plasma ANGPTL4 concentrations throughout pregnancy is positively associated with GWG and could be used as an early marker of increased susceptibility to excess gestational weight gain." (PMID 30127377, 2018). "The objective of this study was to determine whether ANGPTL4 E40K and T266M are associated with triglyceride levels in the setting of obesity and T2D, and whether modification of triglyceride levels by these genetic variants is altered by a lifestyle intervention designed to treat T2D." (PMID 21714923, 2011). "Increased numbers of Allobaculum are associated with higher expression of angiopoietin-like-4 (ANGPTL4) and hepatocyte-specific depletion of Angptl4 protects mice from diet-induced obesity, glucose intolerance, and hepatic steatosis." (PMID 41362710, 2025).
Obesity (continued). "In addition, the strong expansion of the genus Allobaculum, which is known to induce the upregulation of ANGPTL4, a protein associated with diet-induced obesity, glucose intolerance, and hepatic steatosis, may support the development of MASH independent of innate immunity." (PMID 41362710, 2025). "The transcriptomic analysis of term placentas from women with obesity further revealed differential expression of genes associated with lipid metabolism, such as decreased DKK1 (Dickkopf homolog 1) and ANGPTL4 (angiopoietin-like 4)." (PMID 38494514, 2024). "The change of GDCA and TDCA was negatively correlated with obesity-related phenotypes, whereas positively correlated with insulin sensitivity and ANGPTL4 levels." (PMID 38409604, 2024). "Multiple OSA-related factors, such as hypoxia and obesity, result in changes in serum levels of ANGPTL4." (PMID 38574398, 2024). "Spearman’s test was used to analyze correlations of serum ANGPTL4 levels with obesity, lipid levels, and sleep-related breathing parameters." (PMID 38574398, 2024). "Waist circumference, body weight, and other major obesity indicators were negatively correlated with the level of circulating ANGPTL4." (PMID 37170504, 2023). "Here were found many genes whose expression positively correlates with obesity, insulin resistance, type-2 diabetes and chronic inflammation, such as Irs2, Angptl4, Lepr, Camkk2 and Tbk1." (PMID 37957359, 2023). "The constitutive ANGPTL4 knockout in mice was further found to induce resistance to diet-induced obesity, suggesting a promoter role for ANGPTL4 in obesity." (PMID 35409319, 2022). "In conclusion, the inactivation of Angptl4 in mice plays a protective role against the metabolic complications of diet-induced obesity, so that it is currently investigated as a therapeutic strategy for dyslipidemia and to improve glucose intolerance." (PMID 36074318, 2022). "ANGPTL4 is involved in the regulation of lipid metabolism in metabolic syndrome, obesity, diabetes and cardiovascular disease." (PMID 35285130, 2022). "Knocking out or neutralizing ANGPTL4 in mice decreased obesity-induced angiogenesis and tumor growth." (PMID 35186923, 2022). "Further clues about the role of Angptl4 in metabolism and obesity came from genetically engineered mice with deletion of the gene." (PMID 36074318, 2022). "The high levels of IL-1β in response to obesity induce the expression of Angiopoietin-like 4 (ANGPTL4) from primary adipocytes in a manner dependent on NF-κB- and MAPK-activation, which is enhanced by hypoxia." (PMID 33815289, 2021). "Clinical data, fecal bacterial composition, glucose-related hormones, and serum adipokines (adropin and ANGPTL4) were analyzed in 65 Chinese children with exogenous obesity." (PMID 33815293, 2021). "An interplay between VEGF and ANGPTL4 has been described in different diseases, such as obesity and diabetic macular oedema." (PMID 34359826, 2021). "Considering the potential effect of this angiopoietin-like protein on lipid metabolism, a possible relation of ANGPTL4 with obesity was explored." (PMID 33726754, 2021). "Overall, hepatokines including FGF-21, Fetuin-A, ANGPTL4, and follistatin can ameliorate metabolic disorders and lipogenesis in obesity and T2D." (PMID 33498410, 2021). "Under this circumstance, various studies have suggested that ANGPTL4 is involved in the regulation of multiple components of Mets, including lipid metabolism, obesity, blood pressure and glucose tolerance." (PMID 33593372, 2021). "This is meaningful to explore the regulation of ANGPTL4 by gut microbiota in the treatment of obesity." (PMID 34095196, 2021). "In the physiology of obesity, increased FFAs stimulate ANGPTL4 secretion which inhibits LPL activity to reduce lipid loading." (PMID 32641980, 2020).
Obesity (continued). "Butyrate has anti-obesity effects through upstream regulation of the expression of angiopoietin-like protein-4 (ANGPTL4) in human epithelial cells, resulting in the reduced expression of lipoprotein lipase (LPL) and increased lipolysis." (PMID 32668581, 2020). "Our proteomics pathway analyses highlighted other proteins involved in lipoprotein metabolism (APOA1, BMP1, FABP3 and ANGPTL4) and that are key markers in obesity and NAFLD56–58." (PMID 32514005, 2020). "AT represents one of the main sites of action of ANGPTL4 where its expression increases in the fasting state and in obesity, whereas it is suppressed by re-feeding and insulin in experimental models." (PMID 33003532, 2020). "Our observed relationships between muscle ANGPTL4 and measures of obesity are novel, although others have reported relationships with serum ANGPTL4 and total body fat mass." (PMID 32878157, 2020). "It is of great interest that circulating ANGPTL4 in humans is affected by obesity status and altered glucose tolerance, as well as by long-term body weight changes." (PMID 30944669, 2019). "Both children (pre-pubertal stage) and adolescents (pubertal stage) with obesity showed reduced circulating ANGPTL-4 levels with respect to those with normal weight." (PMID 31207920, 2019). "Accordingly, a very recent paper from our group shows that plasma ANGPTL-4 concentration is significantly increased in patients with obesity, especially in those with altered glucose tolerance." (PMID 31207920, 2019). "In the cross-sectional study, circulating ANGPTL-4 levels were lower in children with obesity than in those with normal weight." (PMID 31207920, 2019). "Our findings, in line with previous research, reveal that live probiotics probably affect the intestinal Angptl4 upregulation via surface molecules and prevent obesity." (PMID 31632356, 2019). "The main findings are as follows: First, circulating levels of ANGPTL-4 were decreased in subjects with obesity compared with individuals with normal weight, independent of the gender and pubertal stage." (PMID 31207920, 2019). "Circulating levels of ANGPTL-4 were lower in individuals with obesity than in those with normal weight in the total population." (PMID 31207920, 2019). "Angptl4 is considered a link between the gut microbiota and obesity, preventing FA-induced inflammation." (PMID 31632356, 2019). "In support of this observation, we recently published a report on the significant involvement of ANGPTL-4 in human obesity and type 2 diabetes and its participation in long-term body weight modifications." (PMID 31207920, 2019). "The aim of this study was to better characterise the role of ANGPTL4 in glucose homeostasis and metabolic dysfunction during obesity." (PMID 29502266, 2018). "Analogously, the presence of obesity significantly increased ANGPTL4 while tending to reduce ANGPTL3 suggesting body weight as one of the main regulators of ANGPTL levels." (PMID 29695708, 2018). "Using this model, we characterize in depth the role of adipocyte-specific ANGPTL4 in lipid metabolism, obesity, and atherosclerosis." (PMID 29563332, 2018). "Here we investigated the role of ANGPTL4 in metabolic dysfunction in mice with diet-induced obesity." (PMID 29502266, 2018). "Considering the discussed role about ANGPTL4 in lipid metabolism, a possible link of this angiopoietin-like protein with obesity was investigated." (PMID 28182091, 2017). "Here, we have discussed the potential role of ANGPTL4 in mediating the cross talk between metabolic syndromes, such as diabetes and obesity, and cancer through regulation of its expression by PPARs." (PMID 28182091, 2017). "Plasma levels of Angptl4 were higher in twins with a low body mass index (BMI) as compared to obese counterparts, suggesting an important role of Angptl4 in obesity." (PMID 27617199, 2016). "In conclusion, these observations suggest that Angptl4 is an interesting mediator of microbiota-promoted obesity." (PMID 27617199, 2016).
Obesity (continued). "Butyrate has anti-obesity effects by stimulating the expression of angiopoietin-like protein-4 (ANGPTL4) in human epithelial cells, leading to reduced expression of LPL and increased lipolysis." (PMID 27006755, 2015). "Further investigation is required to determine the role of ANGPTL4 in obesity and obesity-related metabolic abnormalities, such as diabetes." (PMID 21182758, 2010). "Previous studies showed that suppression of Angptl4 by gut microbiota, was related to dietary fat-induced obesity." (PMID 18457598, 2008). "ANGPTL4 regulates fat deposition, and increased levels are related to obesity." (PMID 40765268, 2025). "Notably, PDK4 and ANGPTL4 levels correlate with immaturity and alteration of gastric smooth muscle in patients with obesity." (PMID 40652248, 2025). "The correlation of PDK4 and ANGPTL4 expression with markers of mesenchymal immaturity and smooth muscle dedifferentiation underscores their potential as biomarkers and targets for therapeutic intervention in obesity-related gastric dysmotility." (PMID 40652248, 2025). "We hypothesized that this reduction likely decreased ANGPTL4 expression levels, thereby increasing LPL activity, accelerating lipid metabolism, and reducing the risk of obesity." (PMID 41394914, 2025). "Our findings suggest that B. adolescentis, one of the key species induced by RS, may protect mice against diet-induced obesity by affecting intestinal ANGPTL4." (PMID 38409604, 2024). "Research by Abhishek K using a hepatocyte-specific ANGPTL4 mutant mouse model demonstrated that suppressing ANGPTL4 could prevent diet-induced obesity, reduce ectopic lipid accumulation, and enhance insulin sensitivity and glucose tolerance." (PMID 39176085, 2024). "Furthermore, overweight/obesity was associated with increased expression of CD36 and ANGPTL4 in tumor cells at the invasive front, suggesting altered lipid metabolism and metabolic reprogramming in the tumor cells of these patients." (PMID 39456610, 2024). "In addition, proteomic pathway analyses highlighted other proteins involved in lipoprotein metabolism (APOA1, BMP1, FABP3 and ANGPTL4) that are key markers in obesity and NAFLD." (PMID 36678141, 2023). "Finally, discrepant data between mouse models and patients were observed for the expression of Ahsg and Angptl4, for which we detected an opposite regulation of their mRNA expression with obesity, steatosis and IR." (PMID 35409319, 2022). "Under obesity, IL-1β from primary adipocytes could induce the angiopoietin-like 4 (ANGPTL4) expression through activation of NF-κB and mitogen-activated protein (MAP) kinases, therefore promoting angiogenesis and tumor suppression." (PMID 35701840, 2022). "Studies of mice with the conditional depletion of Angptl4 in adipose tissue demonstrated that, under conditions of diet-induced obesity, gene deletion reduces circulating triglycerides and improves insulin sensitivity, whereas body weight and glucose homeostasis remained unchanged." (PMID 36074318, 2022). "Similarly, blocking Angptl4 is expected to lead to tumor inhibition in the context of obesity, as it reduces the angiogenic potential of the tumors." (PMID 36074318, 2022). "In the mouse model, it was observed that hepatocyte-specific depletion of ANGPTL4 prevents diet-induced obesity, leads to a decrease in circulating triglycerides, increases insulin sensitivity and glucose tolerance and inhibits the progression of atherosclerosis." (PMID 36144281, 2022). "Many studies have reported a positive correlation between circulating ANGPTL4 levels and obesity." (PMID 36077988, 2022). "Moreover, a positive correlation between muscle ANGPTL4, obesity and glucose metabolism has been reported: indeed, ANGPTL4 muscle and serum levels are significantly higher in obese patients with an abnormal glucose tolerance." (PMID 35250605, 2022). "All of these prove that ANGPTL4 is involved in the regulation of gut microbiota on obesity." (PMID 34095196, 2021).